EMC6 (ER membrane protein complex subunit 6)
Description:
Part of the endoplasmic reticulum membrane protein complex (EMC) that enables the energy-independent insertion into endoplasmic reticulum membranes of newly synthesized membrane proteins. Preferentially accommodates proteins with transmembrane domains that are weakly hydrophobic or contain destabilizing features such as charged and aromatic residues. Involved in the cotranslational insertion of multi-pass membrane proteins in which stop-transfer membrane-anchor sequences become ER membrane spanning helices. It is also required for the post-translational insertion of tail-anchored/TA proteins in endoplasmic reticulum membranes. By mediating the proper cotranslational insertion of N-terminal transmembrane domains in an N-exo topology, with translocated N-terminus in the lumen of the ER, controls the topology of multi-pass membrane proteins like the G protein-coupled receptors. By regulating the insertion of various proteins in membranes, it is indirectly involved in many cellular processes (Probable).
Synonyms: TMEM93; MGC2963; RAB5IFL
Tractability: Small molecule: a structure with a bound ligand is known. Antibody: UniProt predicts a signal peptide or a membrane-spanning region. PROTAC: ubiquitination databases record sites on it; its protein half-life has been measured.
Gene: Protein-coding gene on chromosome 17 (3,668,812 to 3,669,668, forward strand). Ensembl gene ENSG00000127774.
Subcellular location: Endoplasmic reticulum membrane
Subcellular location (Human Protein Atlas): Centrosome; Nucleoplasm
Gene Ontology:
Molecular function: membrane insertase activity; protein binding
Biological process: autophagosome assembly; protein insertion into ER membrane by stop-transfer membrane-anchor sequence; tail-anchored membrane protein insertion into ER membrane
Cellular component: EMC complex; endoplasmic reticulum membrane; membrane; omegasome membrane; cytoplasm; endoplasmic reticulum
Genetic constraint (gnomAD): Loss-of-function variants: 1 observed, 6.46 expected, observed/expected ratio (o/e) 0.15, 90% interval 0.054 to 0.73. That is too few expected variants to judge how well the gene tolerates losing a copy. Missense variants: 114 observed, 146.62 expected, observed/expected ratio (o/e) 0.78, 90% interval 0.67 to 0.91. Synonymous variants: 96 observed, 76.85 expected, observed/expected ratio (o/e) 1.25, 90% interval 1.06 to 1.48.
Homologues: Orthologues: chimpanzee EMC6 (100% identical), guinea pig EMC6 (100% identical), macaque EMC6 (100% identical), mouse Emc6 (100% identical), rat Emc6 (100% identical), dog EMC6 (99% identical), pig EMC6 (98% identical), tropical clawed frog emc6 (90% identical), zebrafish emc6 (89% identical), Drosophila melanogaster EMC6 (52% identical), Caenorhabditis elegans emc-6 (39% identical).
Diseases named in the same sentence as EMC6 in open-access papers:
EMC6 is named in the same sentence as 20 diseases in open-access papers, as found by Europe PMC text mining. Sharing a sentence is not in itself a finding about the gene and the disease. The quoted sentences say what the papers report.
gastric cancer (4 papers, 2020 to 2025). A primary or metastatic malignant neoplasm involving the stomach. "In gastric cancer cells, overexpression of EMC6 induces antitumor activity through the mitochondrial apoptosis pathway." (PMID 40384436, 2025). "Meanwhile, EMC6 functions as a tumor suppressor and its overexpression induces apoptosis and cell cycle arrest in gastric cancer cells." (PMID 35222510, 2021). "Previous studies have found that EMC6 protein levels are reduced in gastric cancers but are significantly elevated in cervical cancers, suggesting that the protein may act as either a tumor suppressor or promoter, depending on the cancer type." (PMID 37007952, 2023). "Meanwhile, EMC6 has also been shown to induce cell death in gastric cancer cells." (PMID 33177505, 2020). "Furthermore, EMC6 overexpression significantly inhibited cancer cell growth, induced apoptosis, suppressed the migration and invasion, and exerted strong antitumor activity in gastric cancer cells." (PMID 33177505, 2020). "ER membrane protein complex subunit 6 (EMC6) is a novel positive regulator of autophagy regulator in human cells that has been demonstrated to influence the development of ER stress, and to induce apoptosis in gastric cancer cells." (PMID 35222510, 2021).
osteosarcoma (2 papers, 2016 to 2021). A usually aggressive malignant bone-forming mesenchymal neoplasm, predominantly affecting adolescents and young adults. "EMC6 is an autophagy-related protein that is overexpressed in U2OS osteosarcoma and HCT116 colon carcinoma cells, and that participates in the formation of autophagosomes and in accelerating the degradation of autophagic substrates in lysosomes." (PMID 35222510, 2021).
virus infection (2 papers, 2016 to 2020). "In fact, our data suggest that other EMC subunits, particularly EMC3, EMC4, EMC5, EMC6, EMC7, and EMC10, may also exert roles in supporting virus infection." (PMID 28012275, 2016).
cervical tumor (1 paper, 2022). "According to our previous RNA-seq data, CASP7, EMC6 and PERP were upregulated in cervical tumor tissues, which seemed to conflict with the qPCR results of SFTA1P knockdown." (PMID 36344495, 2022).
epilepsy (1 paper, 2022). A brain disorder characterized by episodes of abnormally increased neuronal discharge resulting in transient episodes of sensory or motor neurological dysfunction, or psychic dysfunction. "Moreover, among ten EMC subunits, EMC3 and EMC6 have the most prominent effect, and overexpression of EMC3 or EMC6 is sufficient to restore the function of epilepsy-associated GABAA receptor variants." (PMID 35938049, 2022).
glioblastoma (1 paper, 2016). The most malignant astrocytic tumor (WHO grade IV). "Our data show that overexpression of EMC6 in three glioblastoma cell lines (SHG44, U87 and U251) suppresses tumor cell growth by activating autophagy, but fails to induce cell apoptosis." (PMID 26775697, 2016). "Overexpression of EMC6 also sensitized glioblastoma cells to the chemotherapy drug, temozolomide, to further suppress tumor growth." (PMID 26775697, 2016). "Our data indicate that EMC6-induced autophagy may play a positive role in suppressing the development of glioblastoma." (PMID 26775697, 2016). "Accordingly, EMC6 knockdown in glioblastoma cells had the opposite effect; it promoted cell growth." (PMID 26775697, 2016).
liver cancer (1 paper, 2024). An epithelial or non-epithelial malignant neoplasm that arises from the liver. "To explore the function of EMC6 in liver cancer, we further conducted KEGG pathway analysis in the TCGA‐LIHC cohort and found that EMC6 was related to the autophagy pathway." (PMID 38445807, 2024).
pancreatitis (1 paper, 2020). Inflammation of the pancreas. "By proteome screening in PRSS1Tg mice pancreatitis tissues, we identified EMC6 and APAF1 as being closely associated with ER stress and apoptosis seen in pancreatic inflammatory diseases." (PMID 33177505, 2020). "Using these mice to screen for ER stress-associated and apoptosis-related proteins involved in pancreatitis development, we identified ER membrane protein complex subunit 6 (EMC6) and apoptotic peptidase activating factor 1 (APAF1) as potential regulatory proteins in pancreatic inflammatory disease." (PMID 33177505, 2020). "In conclusion, by using suitable AP and CP models, we have defined the regulatory relationship between EMC6 and APAF1: EMC6 regulates acinar cell injury via APAF1 in pancreatic inflammatory diseases." (PMID 33177505, 2020). "Our study also showed that following EMC6 inhibition in pancreatitis tissues, the expressions of ER stress markers and APAF1 were ameliorated." (PMID 33177505, 2020). "Our results further suggest that APAF1 is regulated by EMC6, induces apoptosis to injure acinar cells, and promotes inflammation in the development of pancreatitis." (PMID 33177505, 2020). "In the progression of pancreatitis, EMC6 was activated and then upregulated APAF1 to induce acinar cell apoptosis and inflammatory injury." (PMID 33177505, 2020). "However, the mechanism by which EMC6 plays a regulatory role in pancreatitis needs to be further clarified." (PMID 33177505, 2020). "Therefore, we speculated in the present study that EMC6 also induced apoptosis in the pathological context of pancreatitis, and found that ER stress responses and apoptosis were enhanced during pancreatitis progression." (PMID 33177505, 2020). "The expression levels of EMC6 and APAF1 were markedly increased during pancreatitis progression and that APAF1 was positively regulated by EMC6." (PMID 33177505, 2020). "However, the exact mechanism by which EMC6 and/or APAF1 regulate the progression of pancreatitis is unclear and deserves further investigation." (PMID 33177505, 2020).
Salmonella Infections (1 paper, 2023). Infections with bacteria of the genus SALMONELLA. "Among the multiple genes detected in this study, EXFABP, S100A9/12, CEMIP, FKBP5, MAVS, FAM168B, HESX1, EMC6, and others were found as potential candidate gene and transcript (co-) factors for resistance to Salmonella infection." (PMID 36902251, 2023).
cancer (8 papers, 2016 to 2025). A tumor composed of atypical neoplastic, often pleomorphic cells that invade other tissues. "Previous studies have shown that EMC6 positively regulates autophagy and inhibits the migration and invasion of cancer cells." (PMID 38445807, 2024). "Overexpression of EMC6, a subunit of the protein complex found in the endoplasmic reticulum membrane, has been shown to suppress cancer cell growth and trigger apoptosis." (PMID 37965333, 2023). "EMC6 protein reduced PC cells viability and invasion, and cancer patients with high EMC6 expression had longer OS and RFS." (PMID 35222510, 2021). "Moreover, the important role of EMC6 as a therapeutic target for cancer and pancreatic inflammatory diseases has been increasingly recognized." (PMID 35938049, 2022).
tumor (5 papers, 2016 to 2024). "Mechanistically, UBA52 promoted tumour tumorigenesis and metastasis by inhibiting autophagy and decreasing the expression of EMC6." (PMID 38445807, 2024). "For example, the high-risk genes EMC6 and UBE2S were expressed to a greater extent in TCGA-PRAD tumor tissues than in normal tissues." (PMID 37007952, 2023). "To further assess whether tumor suppression was related to autophagy induced by EMC6, we detected LC3B and SQSTM1 by immunofluorescence in the null, mock and EMC6-overexpressing groups of mice." (PMID 26775697, 2016). "Finally, EMC6 expression inhibited the xenograft tumor in in vivo assays in mice." (PMID 26775697, 2016). "Therefore, through inactivation of the mTOR pathway, EMC6 reduces the levels of tumor-forming proteins, which subsequently may inhibit GBM formation." (PMID 26775697, 2016). "Presumably, EMC6 and UBE2S are overexpressed in tumor tissues compared with normal tissues." (PMID 37007952, 2023).
EMC6 also shares sentences with these, for which no sentence is quoted: hepatocellular carcinoma (2 papers); cervical cancer (1); chronic pancreatitis (1); colon carcinoma (1); Flavivirus Infections (1); pancreatic carcinoma (1); prostate carcinoma (1); rectal carcinoma (1); retinal degeneration (1).